PGR (progesterone receptor)
Diseases named in the same sentence as PGR in open-access papers (continued):
Sharing a sentence is not in itself a finding about the gene and the disease.
breast cancer (continued). "Among breast cancer tumors, triple negative breast cancer (TNBC) has poor prognosis, with an 11% 5-year survival rate due to the lack of estrogen receptor (ER), progesterone receptor (PR), and human epidermal growth factor receptor 2 (HER-2)." (PMID 36986473, 2023). "Contrary to other breast cancer (BC) subtypes, TNBC is characterized by the lack of expression of estrogen receptor (ER), progesterone receptor (PGR), and human epidermal growth factor receptor 2 (HER2)." (PMID 36976215, 2023). "Triple negative breast cancer (TNBC), a subtype of breast cancer, refers to breast cancer with negative expression levels of human epidermal growth factor receptor 2 (HER2), estrogen receptor (ER), and progesterone receptor (PR)." (PMID 36064576, 2023). "Thereafter, we compared the correlation between SFRP1 and biomarkers of breast cancer molecular subtyping, such as ESR1, PGR, and HER2 in both breast non-tumoral and tumoral tissues." (PMID 37190179, 2023). "The BLBC presented low expressions of progesterone receptor (PR), estrogen receptor (ER), as well as human epidermal growth factor 2 receptor (HER2), thus also be recognized as a subtype of triple-negative breast cancer (TNBC) which takes up about 10–20% of all BC." (PMID 37507701, 2023). "Triple-negative breast cancer (TNBC), which is defined by the lack of expression of estrogen receptor (ER) and progesterone receptor (PR) and absence of HER2 overexpression and/or gene amplification, accounts for 15% of all breast cancers in the United States." (PMID 35817765, 2022). "TNBC is characterized as estrogen receptor (ER) negative, progesterone receptor (PR) negative, and human epidermal growth factor receptor 2 (HER2) negative, while these receptors are commonly expressed in other subtypes of breast cancer." (PMID 36438660, 2022). "Triple-negative breast cancer (TNBC), which is characterized by negative expression of the estrogen receptor (ER), progesterone receptor (PR), and human epidermal growth factor receptor 2 (HER2), accounts for approximately 15% of all breast cancers." (PMID 36184642, 2022). "Absence of the estrogen receptor (ER), the progesterone receptor (PR), and human epidermal growth factor receptor 2 (HER2) poses a significant barrier compared to other subtypes of breast cancers." (PMID 35454120, 2022). "Differences in the signalling pathways were also observed within the subtypes of triple-negative (i.e., negative for ER, progesterone receptor (PgR) and HER2) breast cancers." (PMID 36361516, 2022). "We further observed a lack of estrogen receptor (ER) and progesterone receptor (PR) expression in carcinomas developing in Lats1/2f/f; lsl-EYFP; K8CreERT2 mammary glands, phenocopying basal-like breast cancers." (PMID 36443313, 2022). "TNBC cells do not express the well-known estrogen receptor, progesterone receptor, and human epidermal growth factor receptor 2 (HER2) expressed by other breast cancer subtypes." (PMID 36483567, 2022). "Triple negative breast cancer (TNBC) is characterized by the clinical absence of ER, PgR and HER2 diagnosed mainly via immunohistochemistry and accounts for 10–20% of all breast cancer." (PMID 35682800, 2022). "MCF-7 cells are commonly used in research for estrogen receptor positive, progesterone receptor positive, and HER2 negative breast cancer cell experiments." (PMID 35330383, 2022). "Breast cancers lacking epidermal growth factor receptor 2 (HER2), estrogen receptor and progesterone receptor, are termed triple-negative breast cancers (TNBC) and are distinguished because of a lack of response to therapies targeting these receptors." (PMID 35203574, 2022). "Other studies also showed that the ER and PgR status was probably not a predictor for pCR, and the ER status was not predictive of pCR in subgroup analyses in HER2-amplified breast cancer patients." (PMID 35663978, 2022).
breast cancer (continued). "The RxPONDER study accrued patients with estrogen receptor and/or progesterone receptor positive (>1%), HER2 negative breast cancers with 1-3 positive lymph nodes, and an Oncotype DX (Exact Sciences, Redwood City, CA) score of 0–25." (PMID 35637226, 2022). "A core needle biopsy of the lump revealed that it was ER and progesterone receptor (PR) positive and human epidermal growth factor receptor 2 (HER-2/neu) negative which confirmed the clinical diagnosis of breast cancer." (PMID 36340541, 2022). "Triple-negative breast cancer (TNBC), defined by the absence of estrogen receptor, progesterone receptor, and overexpression of human epidermal growth factor receptor 2 gene (HR−/HER2−), is a particularly aggressive subtype of breast cancer." (PMID 35941873, 2022). "In cocultures with normal stem cells, we used the following breast cancer cell lines: AMJ13, estrogen, progesterone receptor–negative, and MCF7, progesterone receptor–positive breast cancer cell lines." (PMID 36172043, 2022). "Positive correlations between ARID1A and PGR expression, and negative correlations between EZH2 and PGR/ESR1 expression, were also observed in breast cancer patient samples." (PMID 35326450, 2022). "We examined three cell line models for breast cancer: MCF10A (non-malignant), MCF7 (estrogen and progesterone receptor-positive, metastatic), and MDA-MB-231 (triple-negative, highly metastatic)." (PMID 35203617, 2022). "Triple‐negative breast cancer (TNBC), a heterogeneous subtype characterized by the absence of oestrogen receptor (ER), progesterone receptor (PR) and human epidermal growth factor receptor 2 (HER2), represents 12% to 17% of all breast carcinomas." (PMID 35150062, 2022). "Triple-negative breast cancer (TNBC) is immunohistochemically defined as estrogen receptor (ER)-negative, progesterone receptor (PR)-negative, and human epidermal growth factor receptor 2 (HER2) nonamplified breast cancer." (PMID 33428596, 2021). "The most aggressive, invasive and with poor prognosis type of breast cancer is the triple negative breast cancer (TNBC), which is immunohistochemically characterized by the lack of estrogen receptor, progesterone receptor and absence of HER2 amplification." (PMID 33805741, 2021). "TNBC does not express a progesterone receptor (PR), a tyrosine kinase receptor-2 (ERB2), and an estrogen receptor (ER), so it is insensitive to standard targeted therapeutic agents for breast cancer and can only be treated with chemotherapy." (PMID 33869194, 2021). "Gallen consensus, breast cancer subtypes such as luminal A or B, HER2-positive, and triple-negative are classified based on the positivity of ER or PgR expression, HER2 overexpression, and Ki-67 expression related to cell proliferation." (PMID 34638491, 2021). "TNBC is a type of breast cancer that does not express the estrogen receptor (ER), progesterone receptor (PR) or human epidermal growth factor receptor 2 (HER-2), and accounts for 15–20% of all breast cancers." (PMID 33632232, 2021). "Triple negative breast cancer (TNBC) with estrogen receptor (ER), progesterone receptor (PR) and human epidermal growth factor receptor 2 (HER2) all negative accounts for 15% of all breast cancer." (PMID 34162418, 2021). "This is further supported by our study on single hormone receptor BC, in which miRNA profiles of single hormone receptor-positive breast cancers were mainly dependent on the status of HER2, rather than on ERα/PgR status." (PMID 34638241, 2021). "Triple-negative breast cancer (TNBC), defined by the absence of estrogen receptor (ER), progesterone receptor (PR), and HER2 amplification, is the most highly proliferative breast cancer subtyp." (PMID 34065619, 2021). "Triple-negative breast cancer (TNBC), which represents 15–20% of breast cancers (BC), is classified based on the exclusion criteria of lack of estrogen and progesterone receptor expression and absence of human epidermal growth factor receptor 2 (HER2) overexpression." (PMID 34439290, 2021).
breast cancer (continued). "Triple-negative breast cancer (TNBC) refers to a form of breast malignancy that is negative for the expression of estrogen receptor (ER), progesterone receptor (PR), and human epidermal growth factor 2 (HER2), accounting for 10–15% of human breast cancers." (PMID 34298600, 2021). "Triple negative breast cancer (TNBC), characterized by the absence of estrogen receptor (ER), progesterone receptor (PR), and human epidermal growth factor receptor 2 (HER2) expression, comprises 10–20% of all breast cancers." (PMID 34283088, 2021). "Triple-negative breast cancer (TNBC) is a heterogeneous disease characterized by a lack of estrogen receptor (ER), progesterone receptor (PR), and HER2, and comprise approximately 15–20% of breast cancers." (PMID 33902658, 2021). "In this line, the expression of the estrogen receptor (ER), progesterone receptor (PR), and HER2 biomarkers are related to a better prognosis and response to therapy in breast cancer patients than those with the absence of these biomarkers." (PMID 34944911, 2021). "Triple negative breast cancer (TN) is defined as the absence of estrogen receptor, progesterone receptor, and HER2 expression accounting for approximately 15–20% of all breast cancer patients." (PMID 34442460, 2021). "Triple-negative breast cancer (TNBC) is defined by the absence of expression of the estrogen receptor (ERα), progesterone receptor (PR), and human epidermal growth factor receptor 2 (HER2), and accounts for approximately 10-15% of all breast cancers." (PMID 33867823, 2021). "Triple-negative breast cancer (TNBC) lacks estrogen receptor, progesterone receptor, and HER2 expression and TNBC patients have a higher rate of relapse and a poorer prognosis than other breast cancer patients." (PMID 34445421, 2021). "In the breast cancer patients with the CHEK2 PV in our study, 91.7% had estrogen-receptor-positive cancer, 78.8% had progesterone-receptor-positive cancer and 68.8% had a negative epidermal growth factor receptor 2 (HER2)-status." (PMID 33468213, 2021). "Luminal B-like breast cancer can be further classified as HER2-negative (ER positive, HER2-negative, and with high Ki-67/negative or low PgR) or HER2-positive (ER positive, HER2 overexpressed, or amplified, with any Ki-67 and any PgR)." (PMID 34940072, 2021). "PD-L1 expression is associated with the occurrence of larger tumor size, high grade, estrogen receptor-negative, progesterone receptor-negative, and HER2-positive breast cancer." (PMID 33440868, 2021). "(vi) Immunotherapy appears to be promising for treatment of breast cancer, especially for the case of triple negative breast cancer (TNBC) tumors [tumors negative for ER, progesterone receptor (PR) and HER2]." (PMID 34589428, 2021). "Triple-negative breast cancer (TNBC) is the term used to describe breast cancer cases that lack expression of estrogen receptor (ER), human epidermal growth factor receptor-2 (HER2), and progesterone receptor (PR)." (PMID 32131780, 2020). "Triple-negative breast cancer (TNBC) (estrogen receptor-negative, progesterone receptor-negative, and HER2-negative) is an aggressive subgroup of breast cancer." (PMID 32438621, 2020). "Triple negative breast cancer (TNBC) is defined by a lack of estrogen receptor (ER), progesterone receptor (PR) and human epidermal growth factor 2 receptor (HER2) and remains the most challenging breast cancer to treat." (PMID 32615541, 2020). "The triple-negative breast cancer (TNBC) subtype, which is negative for the progesterone receptor (PR), estrogen receptor (ER), and human epidermal growth factor 2 receptor expression (HER2), accounts for approximately 10% of all the breast cancers." (PMID 32833983, 2020). "Triple-negative breast cancer (TNBC), characterized by the absence of expression of estrogen receptor (ER), progesterone receptor (PR), and human epidermal growth factor receptor 2 (HER2), is the most aggressive and deadly subtype of breast cancer." (PMID 32328175, 2020).
breast cancer (continued). "Triple-negative breast cancer (BC), a kind of BC that does not express the genes for estrogen receptor, progesterone receptor, and HER2/neu, is considered to be more aggressive, have a poorer prognosis, and show a higher recurrence ratio than other types of BCs." (PMID 33519909, 2020). "Triple-negative breast cancers (TNBCs), described as breast cancers negative for progesterone receptor (PR), estrogen receptor (ER), and human epidermal growth factor receptor 2 (HER2), constitute about 15–20% of breast cancer cases." (PMID 33680016, 2020). "Basal-like breast cancer (BLBC) or triple-negative breast cancer (TNBC) is characterized by a lack of hormone receptors (estrogen receptor and progesterone receptor) and high expression or amplification of human epidermal growth factor receptor 2 (HER2)." (PMID 32977861, 2020). "The triple-negative breast cancer (TNBC) is the most severe subtype of breast cancer, and it lacks the expression of human epidermal growth factor receptor 2 (HER2), estrogen receptor (ER), and progesterone receptor (PR)." (PMID 32365495, 2020). "In triple-negative (i.e., estrogen receptor, progesterone receptor and HER2/neu receptor-negative) breast cancer, a highly malignant and therapy-resistant form of breast cancer, CSCs show high levels of Cx26 expression." (PMID 30823688, 2019). "The goal of this study is to show the prognostic value of Ki-67 according to progesterone receptor (PgR) expression in patients who have estrogen receptor- (ER-) positive, human epidermal growth factor receptor 2- (HER2-) negative early breast cancer." (PMID 31975992, 2019). "If a genomic analysis is not available, the patient of low PgR and high Ki-67 expression in active treatment can be considered in the ER-positive and HER2-negative breast cancer." (PMID 31975992, 2019). "Triple-negative breast cancer (TNBC) is characterized by lack of progesterone receptor (PR), estrogen receptor (ER), and human epidermal growth factor receptor 2 (HER2), accounting for about 15–20% of all breast cancer." (PMID 31186039, 2019). "The conventional biomarkers of estrogen receptor (ER), progesterone receptor (PR), and human epidermal growth factor receptor 2 (HER2) are usually not expressed in metaplastic breast cancer (i.e., they are “triple negative” breast cancers)." (PMID 31693690, 2019). "Breast cancers are often classified by the presence or absence of three receptors: estrogen receptor (ESR1), progesterone receptor (PGR), and the HER2 epidermal growth factor receptor (ERBB2)." (PMID 31684899, 2019). "triple‐negative breast cancer (TNBC) is defined as estrogen receptor (ER), progesterone receptor (PR), and human epidermal growth factor receptor‐2 (HER2) negative breast cancer, which accounts for about 10%‐17% of breast cancer molecular subtypes." (PMID 31215169, 2019). "However, there was an observed inverse association between olive oil intake and breast cancer in patients who had undergone Hormone Replacement Therapy (HRT), suggesting that olive oil might have a beneficial effect on oestrogen and progesterone receptor-negative breast cancer patients." (PMID 31505792, 2019). "Although, PIK3CA is not found in treatment guidelines for breast cancer, as is the case for ERBB2, ESR1 or PGR, it is an oncogene found downstream ERBB2." (PMID 31169290, 2019). "Estrogen receptor (ER), progesterone receptor (PR), and human epidermal growth factor receptor 2 (HER-2) are routinely available in breast cancer specimens in routine clinical work without additional tests." (PMID 31929841, 2019). "Triple-negative (estrogen receptor-negative, progesterone receptor-negative, and HER2-negative) breast cancer (TNBC) shares many of the properties of basal-like breast cancer." (PMID 31275376, 2019).
breast cancer (continued). "Triple negative breast cancer (TNBC), which is typically lack of expression of estrogen receptor (ER), progesterone receptor (PR), and human epidermal growth factor receptor 2 (HER2), represents the most aggressive and mortal subtype of breast cancer." (PMID 31088482, 2019). "In a larger breast cancer cDNA array, SOAT mRNA expression was high in almost all adenocarcinoma specimen, but expression did not correlate with either the ER, progesterone receptor, or human epidermal growth factor receptor 2 status." (PMID 30186172, 2018). "Triple negative breast cancer (TNBC), characterized as being negative for estrogen receptor (ER), progesterone receptor (PR), and human epidermal receptor growth factor 2 (HER2), is the second most common breast cancer subtype and has the worst prognosis." (PMID 29698415, 2018). "Luminal-A tumors express estrogen receptor (ER/ESR1) and progesterone receptor (PR/PGR) but not HER2 receptor and accounts for 71% of the breast cancers but are slow growing and less aggressive." (PMID 30335837, 2018). "Conversely, significant prognostic factors for breast cancer are KPS, age and tumor subtype (classified HER2, ER, and PgR status), but not the number of BMs and extracranial metastases." (PMID 29881714, 2018). "In the absence of estrogen receptor (ER) expression, progesterone receptor (PR) expression, and HER2-neu amplification, breast cancer is termed triple-negative breast cancer (TNBC)." (PMID 29617367, 2018). "Luminal breast cancer, defined by the presence of estrogen receptor(ER) and/or progesterone receptor (PgR) and absence of human epidermal growth factor receptor 2 (HER2), is the most common subtype of breast cancer." (PMID 29587760, 2018). "Note that the difference in expression levels of estrogen receptor, progesterone receptor, and HER2 between the different cell lines does not significantly affect the ability of our approach to detect the breast cancer." (PMID 30463284, 2018). "Based on its receptor status, breast cancer is traditionally categorized as ER-positive, PgR-positive, HER2-positive, or triple-negative (ER-negative, PgR-negative, HER2-negative) (TNBC)." (PMID 30559934, 2018). "Triple-negative [Ostrogen receptor (ER-), Progesterone receptor (PgR-), and HER2/neu receptor (HER2-)] breast cancer (TNBC) is an aggressive class of BC characterized by poor prognosis and lacks the benefit of routinely available targeted therapies." (PMID 30458011, 2018). "In contrast, most dimorphic breast carcinomas (non-dimorphic IC and DCIS) are hormonal receptor (ER, PgR) diffusely positive." (PMID 28965222, 2018). "Compared with PDXs of non-luminal subtypes, luminal B breast cancer xenografts, as expected, showed higher mRNA and protein expression of ESR1 and PGR, consistent with their positive ER and PR status." (PMID 28348404, 2017). "Basal‐like breast cancers (BLBCs) underexpress estrogen receptor (ER), progesterone receptor (PR), and human epidermal growth factor receptor 2 (HER2) and encompass 60–90% of triple‐negative (ER−/PR−/HER2−) breast cancers." (PMID 28028927, 2017). "In this case, ‘triple negative’ indicates that no expression of estrogen-receptor (ER), progesterone-receptor (PR), and human epidermal growth factor receptor 2 (HER-2) is found in this type of breast cancer." (PMID 28046018, 2017). "TNBC, which is defined by the negative expression of the estrogen receptor (ER), progesterone receptor (PR) and HER2 receptor, accounts for approximately 15% of all breast cancers." (PMID 27906681, 2017). "Triple-negative breast cancer (TNBC), which do not express estrogen receptor α (ERα), progesterone receptor (PR) and human epidermal growth factor receptor 2 (HER2), accounts for 15% of all breast carcinomas and about 70–80% of basal-like breast cancer." (PMID 28903348, 2017).